NLRP3 (NLR family pyrin domain containing 3)
Diseases named in the same sentence as NLRP3 in open-access papers (continued):
Sharing a sentence is not in itself a finding about the gene and the disease.
gout (continued). "Thus, mitochondrial dysfunction may lead to changes in the mitochondrial membrane potential, release of mitochondrial ROS, and other mechanisms that activate the NLRP3 inflammasome and contribute to the release of IL-1β to promote gout progression." (PMID 35464445, 2022). "Thus, diminishing the production of IL-1β or TNF-α in macrophages by inhibiting the M1 polarization and/or NLRP3 inflammasome activation via the NF-κB signal pathway could be an effective strategy to treat gouty arthritis." (PMID 33505510, 2021). "Notably, the strategies that could either block or reduce the activation of NLRP3 inflammasome could reduce gout inflammation." (PMID 33505510, 2021). "Thus, increased adenosine levels following an inflammatory episode could activate the P1 receptors, exerting anti-inflammatory effects through modulation of the NLRP3 inflammasome, thus, contributing to the resolution of gout flares." (PMID 34925366, 2021). "Recently, it has been reported that tranilast, which is an old and safe clinic drug, could selectively and potently inhibit the NLRP3 inflammasome activation and is effective in mouse models of gout and T2D, while the therapeutic effect of tranilast needs to be further evaluated in clinical trials." (PMID 33350984, 2021). "Therefore, targeting ROS, NLRP3 inflammasome, and its downstream signaling may offer promising therapeutic options for gout." (PMID 33785039, 2021). "However, it has not been examined whether loganin can regulate the activation of the NLRP3 inflammasome and be effective to treat gout." (PMID 33670601, 2021). "However, it remains unclear whether gallic acid can alleviate the inflammatory symptoms of gouty arthritis by inhibiting NLRP3 inflammasome activation and IL-1β expression." (PMID 33365024, 2020). "In addition, our work pointed to the multiplicity of actors (sensors, proteases) that are likely involved in the development of gout, which may advocate against the pharmacological targeting of only one of them, i.e the NLRP3 sensor." (PMID 32104502, 2020). "Hence, we found the intracellular cAMP might be involved in the regulation of P2Y14R on NLRP3 inflammasome-mediated acute gouty arthritis." (PMID 32457291, 2020). "Moreover, wedelolactone could attenuate the MSU‐induced peritonitis and gouty arthritis, suggesting that it also prevented NLRP3 activation in vivo." (PMID 32656909, 2020). "Thus, our results unravel a previously unappreciated mechanism of wedelolactone, which might be a versatile small‐molecule tool to treat NLRP3 stimuli‐induced diseases such as gout." (PMID 32656909, 2020). "Therefore, the therapeutic strategies of wedelolactone to decrease NLRP3 activity and target the pyroptosis could be useful for treating NLRP3‐driven diseases, such as gout, cancer, type 2 diabetes, Alzheimer's, Parkinson's and cardiovascular diseases." (PMID 32656909, 2020). "Therefore, NLRP3 inflammasome inhibitors, a new type of anti‐inflammatory drug candidate that is different from the directly blocking IL‐1β, promise to alleviate arthritis symptoms and limit gout flare." (PMID 32656909, 2020). "Increased NLRP3 expression and activation, together with the release of IL-1β, has been linked to pathogenesis of several painful inflammatory and non-inflammatory conditions such as rheumatoid arthritis, gout, neuropathic pain and diabetic wound healing." (PMID 32973552, 2020). "Since uric acid was first considered a signal sensed by innate immunity (including TLR4 activation and NLRP3 inflammasome in gouty arthritis), the role of uric acid metabolism in immune activation and inflammation has become the current direction and hotspot concerning gout." (PMID 29415757, 2018). "However, corticosteroids also paradoxically induce NLRP3, which may contribute to rebound flares of acute gout after steroid therapy is stopped." (PMID 28818081, 2017). "Thus, CAPE may have preventive or therapeutic potential against NLRP3 inflammasome-related diseases, particularly gout." (PMID 27934918, 2016).
gout (continued). "Therefore, we investigated whether CAPE could suppress uric acid-induced activation of the NLRP3 inflammasome, using bone marrow-derived primary macrophages (BMDMs) and in vivo animal gout models." (PMID 27934918, 2016). "Berberine may influence the NLRP3 inflammasome which is involved in MSU crystals-induced innate immune responses, attenuate the expression of NLRP3, further inhibit downstream signalling molecular IL-1β, and eventually play a role in treatment of gouty arthritis." (PMID 27689075, 2016). "Moreover, NLRP3 inflammasome activation may contribute to insulin resistance and type II diabetes, uric acid accumulation, and gout." (PMID 27433030, 2016). "Given the role of IL-1β in diseases such as type 2 diabetes, gout and osteoarthritis, which all involve NLRP3, a small molecule such as CRID3 could have promise therapeutically and be an alternative to IL-1β biologics such as the anti-IL-1β antibody Canakinumab and the IL-1 Trap Rilonacept." (PMID 22216309, 2011). "By directly targeting IL-17A, miR-23a-5p plays a pivotal role in regulating NLRP3 inflammasome activation both in THP-1 cells and gout rats." (PMID 41578764, 2025). "Results suggest that ER is a potent NLRP3 inhibitor, exerting anti-HUA and anti-gout effects by reducing UA production, enhancing UA excretion, and alleviating inflammation, partly through NLRP3 inflammasome inhibition." (PMID 39968300, 2025). "Inflammasomes, particularly the NLRP3 (NLR family pyrin domain containing 3 inflammasomes), are recognized to be involved not only in gout but also in AD pathogenesis, leading to a proinflammatory state with microglial damage." (PMID 39976039, 2025). "Treatment with a miR-20b inhibitor significantly increased NLRP3 protein levels and IL-1β and TNF-α secretion in MSU-stimulated THP-1 cells, indicating that miR-20b negatively regulates NLRP3 in an in vitro gouty arthritis model." (PMID 41311848, 2025). "Several studies highlight novel small-molecule NLRP3 inhibitors, such as Dapansutrile (OLT1177TM), MCC950, and cucurbitacin B, which effectively reduce MSU-induced inflammation in experimental gout models." (PMID 40430581, 2025). "This study evaluated the synergistic therapeutic potential of ALP and disulfiram (DSF), a known NLRP3 inhibitor in a potassium oxonate (PO) and MSU-induced gouty arthritis model in Wistar rats." (PMID 40430581, 2025). "Gout is a connective tissue disease brought about by crystal-forming MSU through hyperuricemia, leading to inflammation through the NLRP3 inflammasome pathway in immune defense cells." (PMID 39861750, 2025). "In the context of gouty arthritis, USP16 contributes to the inflammatory process through drp1-dependent mitochondrial fission and the activation of the NLRP3 inflammasome." (PMID 40822862, 2025). "Thus, targeting NLRP3 inflammasome activation may serve as a viable strategy for gout treatment." (PMID 41578764, 2025). "Our findings are supported by results from murine models of gouty arthritis, ulcerative colitis, and cytomegalovirus infection, which suggest that targeting ASC can inhibit the activation of the NLRP3 and AIM2 inflammasome and alleviate inflammation." (PMID 39990234, 2025). "Colchicine, that has been the drug of choice for gout attack for more than 200 years, that blocks MSU crystal-induced IL-1β generation upstream of NLRP3 inflammasome activation possibly by suppressing the microtubule-mediated NLRP3 inflammasome assembly." (PMID 39968300, 2025). "For example, in a murine model of gouty arthritis, the compound was found to inhibit the IKK/NF-κB/TXNIP axis, leading to downregulation of NLRP3 and pro-IL-1β expression, ultimately attenuating inflammation and monocyte infiltration." (PMID 41463396, 2025). "Additional research has revealed that circular RNA circHIPK3 promotes inflammation in gouty arthritis by sponging miR-192 and miR-561, thereby enhancing the expression of their target genes TLR4 and NLRP3." (PMID 41311848, 2025).
gout (continued). "Given the growing interest in NLRP3 inhibitors, DSF presents a promising, clinically viable alternative for inflammation control in gout." (PMID 40430581, 2025). "MSU-induced gouty arthritis was generated in conditional knockout mice (Lyz2-Cre-Hectd3fl/fl) and their WT littermates (Hectd3fl/fl), while MCC950, a NLRP3 inhibitor was i.p. injected into these mice." (PMID 38267403, 2024). "Therefore, we speculate that the mechanism of resveratrol in anti-gouty arthritis may involve inhibiting the NLRP3-mediated TLR4/MyD88/NF-κB pathway by regulating relevant metabolic pathways, thereby inhibiting pyroptosis and slowing down the inflammatory response." (PMID 39534253, 2024). "Taken together, these data indicate that ER, a powerful and specific NLRP3 inhibitor, has multiple anti-HUA, anti-gout and anti-inflammatory effects." (PMID 38708084, 2024). "It is known to have therapeutic benefits in NLRP3-mediated diseases in mouse models, such as CAPS, gouty arthritis, and type-2 diabetes." (PMID 38421496, 2024). "To further probe the pathological relevance of NCOA6, we established an in vivo model of gouty arthritis in mice (MSU crystal-induced arthritis), which is another representative model of NLRP3-dependent inflammatory disease." (PMID 38195836, 2024). "In gouty arthritis, MSU activates the NLRP3 inflammasome through the priming signal of NF-κB-dependent transcription of NLRP3 and pro-IL-1β, which triggers a downstream signal upon activation of the TLR 4 receptor." (PMID 39861092, 2024). "This study demonstrates that HECTD3 plays a critical role in MSU-induced gouty arthritis, a NLRP3-related diseases and suggests potential therapeutic strategies for NLRP3-related inflammatory diseases by targeting the HECTD3-NLRP3 interaction." (PMID 38267403, 2024). "The results showed that the expression of NLRP3 and active caspase-1 p20 was elevated in HFD/PO-induced HUA and MSU-induced gouty arthritis mouse models." (PMID 38708084, 2024). "In the past few years, a variety of investigations have addressed the critical role of NLRP3 inflammasome activation in the onset and development of HUA and gout." (PMID 38708084, 2024). "In gout, MSU crystals stimulate the macrophage by activating NLRP3 inflammasome, triggering the release of pro-inflammatory cytokines." (PMID 38240927, 2024). "MCC950 treatment significantly alleviated NLRP3, Caspase-1 and IL-1β protein overexpression in ankle joint tissues of gout model mice compared with vehicle-treated (control) group, confirming the effectiveness of MCC950 on NLRP3 inflammasome." (PMID 37464384, 2023). "In patients with gout, chronic deposition and presence of MSU crystals in the joints, facilitates on-going gouty flares underpinned by high systemic levels of NLRP3-derived IL-1β." (PMID 37106238, 2023). "The NOD-like receptor family, pyrin domain containing 3 (NLRP3) inflammasome can be activated by MSU crystals, resulting in the production of its downstream effectors interleukin (IL)-1β and IL-18 in gout patients." (PMID 36814289, 2023). "Procyanidins, derived from grape seed, significantly attenuated gout pain and ankle swelling in MSU-induced GA mouse model by inactivating NLRP3 inflammasome and reducing IL-1β release." (PMID 37051231, 2023). "One study showed that NLRP3 activation by MSU crystals resulted in marked neutrophil infiltration and the onset of pyroptosis in a rat model of gout." (PMID 37250902, 2023). "NLRP3 inflammasome mediates the development of many inflammatory diseases, like NASH, acute lung injury, gout, type 2 diabetes, and preeclampsia." (PMID 37400760, 2023). "In our previous study, we confirmed that WSP exerted an anti-gout effect by inhibiting MAPK, NF-κB, and NLRP3 signaling pathways in MSU-stimulated THP-1 macrophages." (PMID 37637422, 2023). "Research has demonstrated an elevation in the expression of NLRP3, ASC, IL-1β, and Caspase-1 in joint tissues during the progression of gout." (PMID 38094893, 2023).
gout (continued). "Oridonin, a major active ingredient of the traditional Chinese medicinal herb Rabdosia rubescens, covalently binds to cysteine 279 of NLRP3 and blocks its interaction with NEK7 to limit gouty arthritis." (PMID 37598797, 2023). "DSF inhibits NLRP3 activation by inhibiting mitochondrial ROS production and has a significant effect on MSU‐induced gout inflammation." (PMID 37125240, 2023). "Our results demonstrate that EA reduces gout pain possibly through suppressing ROS-mediated NLRP3 inflammasome activation in inflamed ankle joints and TRPV1 upregulation in sensory neurons, supporting EA as a treatment option for gout pain." (PMID 37464384, 2023). "Even though the NLRP3 inflammasome is considered to be a key mechanism in explaining the pathogenesis of gout, the clinical relevance of PPAR-γ to gouty arthritis remains elusive." (PMID 37111279, 2023). "The inflammatory mechanism of gout is not fully understood, but it is widely believed that the NOD-like receptor family, pyrin domain-containing 3 (NLRP3) inflammasome and Toll-like receptor (TLR) signaling pathway play important roles." (PMID 36339582, 2022). "NLRP3 inflammasomes activate IL-1β by activating caspase-1 and then activate the NOD receptor family signaling pathway to induce gout inflammation." (PMID 35449811, 2022). "Inhibits NLRP3 assembly by blocking NLRP3 oligomerization through direct binding to the NACHT structural domain and shows ex vivo activity toward monocytes from gout patients." (PMID 35464445, 2022). "Extracellular ATP is a signaling molecule that acts on P2X7R to activate the NLRP3-caspase-1-IL-1β signaling pathway, aggravating MSU crystal-induced gout pathogenesis." (PMID 36052144, 2022). "The inflammatory process of gout is mediated by the phagocytosis of MSU crystals and activation of the NLRP2 and NLRP3 inflammasome." (PMID 36447664, 2022). "Activation of the NLRP3 inflammasome and the subsequent release of IL-1β are critical steps in the initiation of the acute inflammatory response to MSU crystals during a gout flare." (PMID 36064735, 2022). "Extracellular UA and MSU have been recognized by TLR2 and TLR4 in gouty arthritis and activate the MAPK, NLRP3 and NF-κB signaling pathways, thus initiating the inflammatory response." (PMID 36438835, 2022). "Purine guanosine monophosphate receptor P2Y14R negatively regulates NLRP3 inflammasomes, and in mice with knockout of the P2Y14R gene, NLRP3 expression and MSU-related pyroptosis were downregulated, while gout symptoms were alleviated." (PMID 36142364, 2022). "In conclusion, ELB is protective in rats with chronic alcoholic liver injury and gouty arthritis, possibly mediated by the inhibition of TLR4/MyD88/NF-κB, NLRP3, and JAK2-STAT3 signaling pathways in both the hepatic and synovial tissues." (PMID 36176434, 2022). "MiR-449a and miR-192-5p can target NLRP3 and epiregulin (EREG) to inhibit macrophage M1 polarization in gout." (PMID 36034424, 2022). "The initiation of gout occurs because of the interaction between MSU and resident macrophages, which activate the NLRP3 inflammasome complex, a regulator of the pro-inflammatory cytokine, IL-1β." (PMID 35400961, 2022). "For the occurrence of gout flares, monosodium urate (MSU) crystal-induced nod-like receptor protein 3 (NLRP3) inflammasome activation is the central link in initiating the inflammatory response." (PMID 36052144, 2022). "In addition, Cyclocarya paliurus ameliorates hyperuricemia and gout via a mechanism that may involve 3β,23-dihydroxy-12-ene-28-ursolic acid, a potent substance derived from C. paliurus that inhibits NLRP3 inflammasome formation via PI3K/Akt/mTOR-dependent autophagy." (PMID 35464445, 2022). "Probiotic intervention is promising for modulating the NLRP3 inflammasome signaling pathway to improve HUA and gout." (PMID 36034697, 2022). "In this review, we present background information on gout and the activation of NLR family pyrin domain containing 3 (NLRP3) inflammasome." (PMID 35370689, 2022).